MAPK9 (mitogen-activated protein kinase 9)
Description:
Serine/threonine-protein kinase involved in various processes such as cell proliferation, differentiation, migration, transformation and programmed cell death. Extracellular stimuli such as pro-inflammatory cytokines or physical stress stimulate the stress-activated protein kinase/c-Jun N-terminal kinase (SAP/JNK) signaling pathway. In this cascade, two dual specificity kinases MAP2K4/MKK4 and MAP2K7/MKK7 phosphorylate and activate MAPK9/JNK2. In turn, MAPK9/JNK2 phosphorylates a number of transcription factors, primarily components of AP-1 such as JUN and ATF2 and thus regulates AP-1 transcriptional activity. In response to oxidative or ribotoxic stresses, inhibits rRNA synthesis by phosphorylating and inactivating the RNA polymerase 1-specific transcription initiation factor RRN3. In T-cells, MAPK8 and MAPK9 are required for polarized differentiation of T-helper cells into Th1 cells. Upon T-cell receptor (TCR) stimulation, is activated by CARMA1, BCL10, MAP2K7 and MAP3K7/TAK1 to regulate JUN protein levels. Plays an important role in the osmotic stress-induced epithelial tight-junctions disruption. When activated, promotes beta-catenin/CTNNB1 degradation and inhibits the canonical Wnt signaling pathway. Also participates in neurite growth in spiral ganglion neurons (By similarity). Phosphorylates the CLOCK-BMAL1 heterodimer and plays a role in the regulation of the circadian clock. Phosphorylates POU5F1, which results in the inhibition of POU5F1's transcriptional activity and enhances its proteasomal degradation (By similarity). Phosphorylates ALKBH5 in response to reactive oxygen species (ROS), promoting ALKBH5 sumoylation and inactivation. MAPK9 isoforms display different binding patterns: alpha-1 and alpha-2 preferentially bind to JUN, whereas beta-1 and beta-2 bind to ATF2. However, there is no correlation between binding and phosphorylation, which is achieved at about the same efficiency by all isoforms. JUNB is not a substrate for JNK2 alpha-2, and JUND binds only weakly to it.
Synonyms: SAPK1a; JNK2; PRKM9; p54a; SAPK; JNK-55; JNK2A; JNK2ALPHA; JNK2B; JNK2BETA; p54aSAPK
Tractability: Small molecule: a drug acting on it is in phase 2 or 3 trials; a structure with a bound ligand is known; a high-quality ligand is known; it has a high-quality binding pocket; it belongs to a druggable protein family. Antibody: its Gene Ontology location is reachable by antibodies, with high confidence. PROTAC: it is named in the literature on targeted protein degradation; ubiquitination databases record sites on it; its protein half-life has been measured; a small molecule that binds it is known.
Target class: Protein Kinase; CMGC protein kinase JNK subfamily; Enzyme; Kinase; CMGC protein kinase group; CMGC protein kinase MAPK family
Chemical probes: BIRB-1017, JNK-IN-7 (high quality), PD080706, PD081343, PD082263, PD083708, PD084913, PD084937, PD134319
Gene: Protein-coding gene on chromosome 5 (180,233,143 to 180,292,099, reverse strand). Ensembl gene ENSG00000050748.
Subcellular location: Cytoplasm; Nucleus
Subcellular location (Human Protein Atlas): Cytosol; Plasma membrane; Nuclear speckles
Pathways (Reactome):
Immune System: Activation of the AP-1 family of transcription factors; FCERI mediated MAPK activation; JNK (c-Jun kinases) phosphorylation and activation mediated by activated human TAK1
Cellular responses to stimuli: Oxidative Stress Induced Senescence
Disease: Signaling by ALK fusions and activated point mutants
Gene Ontology:
Molecular function: JUN kinase activity; protein binding; protein serine kinase activity; protein serine/threonine kinase activity; ATP binding; MAP kinase activity; protein kinase activity; protein serine/threonine/tyrosine kinase activity
Biological process: cellular response to reactive oxygen species; inflammatory response to wounding; JNK cascade; positive regulation of cytokine production involved in inflammatory response; positive regulation of gene expression; positive regulation of macrophage derived foam cell differentiation; protein phosphorylation; cellular senescence; Fc-epsilon receptor signaling pathway; regulation of circadian rhythm; MAPK cascade; modulation of chemical synaptic transmission; positive regulation of proteasomal ubiquitin-dependent protein catabolic process; positive regulation of protein ubiquitination
Cellular component: cytoplasm; cytosol; nuclear speck; nucleus; nucleoplasm; mitochondrion; Schaffer collateral - CA1 synapse
Genetic constraint (gnomAD): Loss-of-function variants: 22 observed, 46.83 expected, observed/expected ratio (o/e) 0.47, 90% interval 0.34 to 0.67. The upper end of that interval is the gene's LOEUF score, 0.67, which puts it in group 2 of 6, group 1 being the genes least tolerant of losing a copy. Missense variants: 301 observed, 455.82 expected, observed/expected ratio (o/e) 0.66, 90% interval 0.6 to 0.73. Synonymous variants: 139 observed, 163.63 expected, observed/expected ratio (o/e) 0.85, 90% interval 0.74 to 0.98.
Homologues: Orthologues: chimpanzee MAPK9 (100% identical), guinea pig MAPK9 (99% identical), pig MAPK9 (99% identical), dog MAPK9 (99% identical), mouse Mapk9 (99% identical), macaque MAPK9 (98% identical), rabbit MAPK9 (88% identical), rat Mapk9 (88% identical), zebrafish mapk9 (84% identical), Caenorhabditis elegans kgb-1 (43% identical), Caenorhabditis elegans kgb-2 (39% identical), Caenorhabditis elegans pmk-1 (38% identical), and 8 more. Paralogues in human: MAPK10 (85% identical), MAPK8 (82% identical), MAPK14 (45% identical), MAPK11 (41% identical), MAPK12 (40% identical), MAPK13 (39% identical), MAPK7 (36% identical), MAPK1 (34% identical), MAPK3 (34% identical), MAPK15 (32% identical), NLK (32% identical), CILK1 (28% identical), and 7 more.
Diseases named in the same sentence as MAPK9 in open-access papers:
MAPK9 is named in the same sentence as 177 diseases in open-access papers, as found by Europe PMC text mining. Sharing a sentence is not in itself a finding about the gene and the disease. The quoted sentences say what the papers report.
breast cancer (55 papers, 2009 to 2026). A primary or metastatic malignant neoplasm involving the breast. "Firstly, we examined the expression and phosphorylation of JNK1 (MAPK8) and JNK2 (MAPK9) in ER+ breast cancer using UALCAN data." (PMID 40826108, 2025). "We developed multiple CRISPR/Cas9 knockout ER+ breast cancer cell lines (MCF-7 and T-47D) to investigate the effects of MAP2K7 and downstream MAPK8 and MAPK9 loss." (PMID 40826108, 2025). "Taking these analyses into consideration, we propose that PRKCB and MAPK9 can be additional prognosis markers and can be used in precision medicine for breast cancer patients." (PMID 32241917, 2020). "Moreover, a large amount of evidence showed that MAPK9 signaling is related to lung cancer, breast cancer, colon cancer, and ovarian cancer, mainly to adenocarcinoma cells." (PMID 32140076, 2020). "This study employed phosphoproteomic analysis to investigate ARID1A phosphorylation in breast cancer, identifying predominant phosphosites-S363, S1184, and S696-regulated by kinases such as MAPK14, CDK16, and MAPK9." (PMID 41572083, 2026). "ER+ breast cancers with MAPK8 deletions had on average 21.6% lower JNK activity, whereas cancers with MAPK9 deletion had 26.9% lower JNK phosphorylation than those without MAPK9 deletions." (PMID 40826108, 2025). "The expression levels of Prss14/epithin (ST14), PKCβ (PRKCB), and three JNKs (MAPK8, MAPK9, and MAPK10) in more aggressive ER-negative (ER−) and less aggressive ER-positive (ER+) breast cancer patients were compared individually in the plot." (PMID 32241917, 2020). "Furthermore, JNK knockdown decreases ER+ breast cancer cell proliferation, an observation that we also see with MAPK8 or MAPK9 knockdown." (PMID 40826108, 2025).
Insulin resistance (25 papers, 2013 to 2026). Increased resistance towards insulin, that is, diminished effectiveness of insulin in reducing blood glucose levels. "It is likely that the high expression of MAPK9 is involved in integrating insulin production, insulin resistance, and MAPK and prolactin production signaling to increase lipid synthesis in the liver." (PMID 31456815, 2019). "Interestingly, recent studies have shown that the knockdown of Mapk9 leads to reduced serum levels of glucose, insulin, and homeostatic model assessment and therefore reverses insulin resistance in HFD-fed mice." (PMID 23555558, 2013). "Stress regulators MAPK9 and PTEN were further enriched in insulin resistance (hsa04931), diabetic cardiomyopathy (hsa05415), and FoxO signaling (hsa04068)." (PMID 41208460, 2025).
colon carcinoma (21 papers, 2009 to 2023). "Synbiotics intervention increased glutathione‐S‐transferase mu‐1 (GSTM1) and decreased MAPK9 gene expression in colon tumors, thereby attenuating the promotive and progressive effects of indole‐3 carbinol on colon carcinogenesis and reducing the risk of colon cancer in rats." (PMID 37937304, 2023). "Similarly, five genes including TOP2A, REL, SHH, ROS1, and CHEK2 in colon cancer gene network and three genes including RBL1, MAPK9, and PIK3CA in adenocarcinoma of lung gene network are selected." (PMID 29670664, 2018).
hepatocellular carcinoma (21 papers, 2008 to 2025). A malignant tumor that arises from hepatocytes. "Circular RNA derived from the mitogen-activated protein kinase 9 (Circ_MAPK9) influences hepatocellular carcinoma progression through silencing miR-642b-3p, thereby promoting the STAT3 and LDHA expression." (PMID 38829380, 2025).
colorectal cancer (18 papers, 2009 to 2025). A primary or metastatic malignant neoplasm that affects the colon or rectum. "Kaplan–Meier survival analysis showed that high expression of GSR, CALM1, and MAPK9 was significantly associated with better prognosis in colorectal cancer patients." (PMID 40696679, 2025). "For RIG-I-like receptor signaling pathway in colorectal cancer, MAPK9, MAPK14, MAP3K7, and RELA were enriched in the pathway." (PMID 39211773, 2024). "Specifically, we found that a subgroup of seven genes – BIRC5, CYCS, FZD3, FZD8, MAPK9, SMAD3, and SOS1 – that belong to the KEGG colorectal cancer pathway showed significant association with risk of BCC." (PMID 27367190, 2016). "The heatmap of individual samples, revealed a trend of high Bcl6, low Dlg2 and high MAPK9 in many colorectal carcinoma samples relative to the normal intestinal mucosa." (PMID 26187947, 2015). "The results showed that, compared with normal tissues, the expression of ADRA1B, CDKN2A, FCER2, and IL13 was significantly upregulated in colorectal cancer tissues, while CALM1, CTNNA1, GSR, INSR, and MAPK9 were significantly downregulated." (PMID 40696679, 2025). "Around half of the CRLM1 peak genes were related to either increased or decreased gene expression, including increased expression of colorectal cancer genes SMAD2, MAPK9, and GSK3β, as well as three members of GALNT family." (PMID 35907898, 2022). "Hypermethylation of the MAPK9 promoter region affected the MAPK signaling pathway, focal adhesion, and Wnt signaling pathway in colorectal cancer (CRC)." (PMID 33126898, 2020). "MAPK9 belongs to the MAPK pathway, it has been reported that genetic variation in the MAPK signaling pathway genes can mediate cell proliferation and migration of colorectal cancer cells." (PMID 35783272, 2022).
pancreatic cancer (18 papers, 2012 to 2024). "In this study, the knockdown of CCNI2 led to the upregulation of MAPK9 in pancreatic cancer cells." (PMID 37540586, 2024). "Interestingly, the results of the two studies seem to be consistent: 6 genes are shared within the first top 20 ranked genes, and in particular, KRAS and MAPK9 are both elements of the pancreatic cancer pathways." (PMID 31652275, 2019). "High and low MAPK9 expression is also involved in multiple cancer pathways, such as colorectal and bladder cancers.High and low TP63 expression is involved in various diseases such as Parkinson’s disease and pancreatic cancer." (PMID 34168974, 2021).
prostate carcinoma (16 papers, 2000 to 2024). A carcinoma that arises from epithelial cells of the prostate gland. "For example, MAPK9 is a contributor to the development and progression of glioma, prostate carcinoma or lung carcinoma, but acts as a negative regulator in cellular proliferation." (PMID 35854294, 2022).
diabetes (14 papers, 2006 to 2025). "In the GSE25724 data set, diabetes was also associated with lower MAPK9 gene expression." (PMID 40696679, 2025). "In the GSE20966 cohort, diabetes was associated with lower GSR and MAPK9 gene expression compared with nondiabetic controls." (PMID 40696679, 2025).
glioma (14 papers, 2010 to 2022). A benign or malignant brain and spinal cord tumor that arises from glial cells (astrocytes, oligodendrocytes, ependymal cells). "In the subnetworks, several kinases, such as ABL1, ACVR1, EPHA4, MAPK9, PAK1 and SRC, were commonly associated with glioma, cell migration and cell death/survival." (PMID 32392905, 2020). "Of these, MAPK9 was found to be significantly upregulated in glioma stem cells." (PMID 32293263, 2020). "The results showed that MLK3 mRNA in human gliomas was negatively related to MAPK8, MAPK9, and MAPK10." (PMID 33692940, 2020). "Some intriguing aspects of the core gene set identified in this study include the well-studied glioma-related genes ANGPT2, CD44, SPP1, STAT3, PDGRFA, and TOP2A (all up-regulated), and BRSK1, DKK3, FGFR2, MAPK9, MEF2C, and PTEN (all down-regulated)." (PMID 29352201, 2018).
melanoma (13 papers, 2013 to 2025). A malignant, usually aggressive tumor composed of atypical, neoplastic melanocytes. "A recent study has shown that MAPK9 activity played an indispensable part in invasiveness and BRAFi resistance of melanoma cell." (PMID 33178587, 2020).
bladder cancer (12 papers, 2015 to 2022). "MAPK9 signaling pathway is reported to have regulatory roles in non-small cell lung cancer, bladder cancer, cholangiocarcinoma and other cancers." (PMID 36203871, 2022).
lung carcinoma (10 papers, 2010 to 2025). "This is followed by up-regulating Mitogen-activated protein kinase 9 (MAPK9) to promote the development of lung cancer." (PMID 39912974, 2025). "MIAT may work as a ceRNA to control lung cancer cell invasion, migration, and proliferation by forming a feedback loop involving MAPK9 and miR-106." (PMID 39912974, 2025).
steatosis (9 papers, 2016 to 2025). Increased lipid within the cytoplasm of cells. "Surprisingly, intake of 67 % High BCAA ameliorates NAFLD by inhibiting tryptophan-ILA-AHR and activating MAPK9 ubiquitination, inhibiting DNL and steatosis, increasing hepatic insulin sensitivity, promoting ketogenesis and fatty acid oxidation via activating PPAR-RXR and pexophagy." (PMID 39426289, 2024).
glioblastoma (8 papers, 2010 to 2025). The most malignant astrocytic tumor (WHO grade IV). "MAPK9 is also called JNK2; recent studies have highlighted the oncogenic potential of MAPK9 in several human cancer cells, such as lung and glioblastoma." (PMID 35036428, 2022).
depression (6 papers, 2016 to 2024). "However, the evidence demonstrated that the analyzed anxiety- and depression-related DEGs such as Gria1, Mapk1, Mapk9, and Fkbp5 contributed to anxiety or depression symptoms in rodents." (PMID 33898422, 2021).
ischemia (5 papers, 2009 to 2021). A hypoperfusion of the BLOOD through an organ or tissue caused by a PATHOLOGIC CONSTRICTION or obstruction of its BLOOD VESSELS, or an absence of BLOOD CIRCULATION. "There was a marked increase in Mapk10 RNA expression in peripheral nerves with ischemia without any change in other members of the JNK family (Mapk8 and Mapk9) that are expressed in neurons." (PMID 31530804, 2019).
colitis (4 papers, 2023 to 2024). Inflammation of the colon. "In control animals, Mapk9 mRNA was upregulated in the colon due to the absence of Muc13 expression, whereas the mRNA levels of Mapk1, Mapk9, Rock2 and Snai1 were also affected upon acute colitis in Muc13−/− mice compared to their wildtype counterparts." (PMID 37174625, 2023).
gastric cancer (4 papers, 2016 to 2021). A primary or metastatic malignant neoplasm involving the stomach. "In this study, western blot analysis found that CCNI2 knockdown resulted in reduced AKT phosphorylation level, downregulated CCND1 and CDK1, upregulated MAPK9 expression in gastric cancer cells." (PMID 34895232, 2021).
Hepatic steatosis (4 papers, 2016 to 2025). Steatosis is a term used to denote lipid accumulation within hepatocytes. "In summary, these results jointly demonstrate that the inhibition of AHR/MAPK9 mediated by tryptophan-ILA ligand depletion is both sufficient to ameliorate NAFLD-related hepatic steatosis and required for a High BCAA to maximally ameliorate metabolic health." (PMID 39426289, 2024). "Our most striking finding was that tryptophan-ILA depletion induced by High BCAA feeding led to AHR/MAPK9-mediated hepatic steatosis and DNL downregulation." (PMID 39426289, 2024). "High BCAA diet-induced hepatic steatosis and DNL are downregulated by AHR and MAPK9, which can be explained by the reduction of AHR ligand ILA in the circulation and the liver." (PMID 39426289, 2024).
type 2 diabetes (4 papers, 2013 to 2021). "However, further studies are required to elucidate the precise function of Mapk9 in the development of HFD-induced type 2 diabetes." (PMID 23555558, 2013).
Anxiety (3 papers, 2020 to 2021). Intense feelings of nervousness, tension, or panic often arise in response to interpersonal stresses. "Whole exome sequencing and whole genome sequencing revealed extensive regions of opposite homozygosity in the same locus on chromosome 11 between the cases and controls with interesting neuronal candidate genes such as MAPK9/JNK2, a known hippocampal regulator of anxiety." (PMID 32467585, 2020).
neuroblastoma (3 papers, 2016 to 2022). Neuroblastoma (NB) is the most common solid, extracranial childhood tumor. "Neuroblastoma cells were sensitive to JNK-IN-840 and SP60012541, but not the MAPK9/10 selective compound CC-93042, which lacked effect even at high doses." (PMID 31900415, 2020).
non-small cell lung carcinoma (3 papers, 2022 to 2025). A group of at least three distinct histological types of lung cancer, including non-small cell squamous cell carcinoma, adenocarcinoma, and large cell carcinoma. "As a key member in the MAPK signaling pathway, MAPK9 is also correlated with several diseases, including non-small-cell lung carcinoma, haemophilia A, and type I diabetes." (PMID 34996511, 2022).
prostate tumors (3 papers, 2011 to 2018). "Expression of the MAPK9 gene is higher in metastatic prostate tumors than in primary prostate tumors." (PMID 29535815, 2018). "Compared to the normal prostate tissues or primary prostate tumors, the mRNA levels of DVL3, MAPK9, and CTNNB1 are higher in metastatic prostate tumors while the mRNA level of ROR2 is lower in metastatic prostate tumors." (PMID 27191743, 2016). "Gene expression of FZD5, DVL3, RELA, MAPK9, CTNNB1, and SNAI1 is higher in metastatic prostate tumors as compared to primary prostate tumors." (PMID 27191743, 2016).